DRD5 (dopamine receptor D5)
Description:
Dopamine receptor whose activity is mediated by G proteins which activate adenylyl cyclase.
Synonyms: DRD1B; DRD1L2; DBDR
Tractability: Small molecule: an approved drug acts on it; a structure with a bound ligand is known; a high-quality ligand is known; it belongs to a druggable protein family. Antibody: its Gene Ontology location is reachable by antibodies, with high confidence; UniProt places it where antibodies can reach, with medium confidence; UniProt predicts a signal peptide or a membrane-spanning region. PROTAC: a small molecule that binds it is known. Other modalities: an approved drug acts on it.
Target class: Small molecule receptor (family A GPCR); Dopamine receptor; Family A G protein-coupled receptor; Monoamine receptor; Membrane receptor
Gene: Protein-coding gene on chromosome 4 (9,781,387 to 9,784,012, forward strand). Ensembl gene ENSG00000169676.
Subcellular location: Cell membrane
Pathways (Reactome):
Signal Transduction: Dopamine receptors; G alpha (s) signalling events
Gene Ontology:
Molecular function: dopamine binding; dopamine neurotransmitter receptor activity; dopamine neurotransmitter receptor activity, coupled via Gs; protein binding; G protein-coupled receptor activity
Biological process: adenylate cyclase-activating dopamine receptor signaling pathway; adenylate cyclase-activating G protein-coupled receptor signaling pathway; cellular response to catecholamine stimulus; reactive oxygen species metabolic process; regulation of blood pressure; adenylate cyclase-activating adrenergic receptor signaling pathway; chemical synaptic transmission; G protein-coupled dopamine receptor signaling pathway; intracellular calcium ion homeostasis; phospholipase C-activating dopamine receptor signaling pathway; positive regulation of adenylate cyclase activity; positive regulation of MAPK cascade; synaptic transmission, dopaminergic; G protein-coupled receptor signaling pathway
Cellular component: ciliary membrane; cilium; non-motile cilium; plasma membrane; 9+0 non-motile cilium; brush border membrane; membrane; synapse
Genetic constraint (gnomAD): Loss-of-function variants: 2 observed, 2.25 expected, observed/expected ratio (o/e) 0.89, 90% interval 0.34 to 1.85. That is too few expected variants to judge how well the gene tolerates losing a copy. Missense variants: 758 observed, 664.07 expected, observed/expected ratio (o/e) 1.14, 90% interval 1.08 to 1.21. Synonymous variants: 327 observed, 276.7 expected, observed/expected ratio (o/e) 1.18, 90% interval 1.08 to 1.29.
Homologues: Orthologues: chimpanzee DRD5 (99% identical), macaque DRD5 (96% identical), dog DRD5 (87% identical), mouse Drd5 (83% identical), guinea pig DRD5 (82% identical), rat Drd5 (82% identical), pig DRD5 (80% identical), rabbit DRD5 (80% identical), tropical clawed frog drd5 (65% identical), zebrafish DRD5 (47% identical). Paralogues in human: DRD1 (53% identical), HTR4 (26% identical), HTR1A (26% identical), DRD4 (23% identical), DRD3 (23% identical), HRH2 (23% identical), CHRM3 (23% identical), HTR1D (23% identical), TAAR1 (22% identical), CHRM1 (21% identical), CHRM2 (21% identical), CHRM4 (21% identical), and 13 more.
Diseases named in the same sentence as DRD5 in open-access papers:
DRD5 is named in the same sentence as 62 diseases in open-access papers, as found by Europe PMC text mining. Sharing a sentence is not in itself a finding about the gene and the disease. The quoted sentences say what the papers report.
schizophrenia (11 papers, 2011 to 2025). A major psychotic disorder characterized by abnormalities in the perception or expression of reality. "Previous studies have confirmed a strong association between genetic polymorphisms in the DRD5 gene and synaptic plasticity impairments in schizophrenia." (PMID 41394403, 2025). "OLZ treatment in rats affected the 5mC levels of several genes associated with schizophrenia, including dopamine D1 receptor (DRD1), dopamine D2 receptor (DRD2), dopamine D5 receptor (DRD5), and others." (PMID 38203806, 2024). "Biological pathways have been proposed and pursued, centering on the schizophrenia-linked candidate neurotransmitter dopamine; in rodents, infection with T. gondii leads to aberrant dopamine signaling and reduced expression of genes within the dopamine pathway, such as DRD1, DRD5 and MAOA." (PMID 26886853, 2016). "On the other hand, the antagonists targeting GABRG-3, GABRG-4, DRD5, ADR -A1D/–B2, CHRM-3, and SLC6A4 (all elevated by FD) are under investigation for treating bipolar disorder and schizophrenia." (PMID 24632812, 2014).
breast carcinoma (7 papers, 2018 to 2025). "DRD5 is a biomarker associated with ferroptosis that can be used for disease diagnosis and treatment monitoring in breast cancer." (PMID 38178888, 2023). "The overexpression of DRD2 and DRD3, with concomitant silencing of DRD5 expression, confirms the presence of dopaminergic abnormalities in breast cancer patients." (PMID 38928253, 2024). "DRD2 is an agonist of DRD5, and its high expression has been reported in many cancers, including breast cancer, ovarian cancer, and lung cancer." (PMID 34768458, 2021). "In 12 tumor types including bladder cancer, breast cancer, esophageal squamous cell carcinoma, and head and neck cancer, hypermethylation in the DRD5 promoter region leads to gene expression silencing, whereas in non-small cell lung cancer, DRD5 expression was elevated in response to docetaxel." (PMID 40873563, 2025). "In addition, the dopamine receptor D5 gene (DRD5) was described to be involved in tumor growth inhibition via autophagic cell death, NCOR2 was described to be associated with drug resistance in breast cancers and CRISP3 was associated with prostate and ovarian cancers." (PMID 33400739, 2020).
Hypertension (7 papers, 2013 to 2023). The presence of chronic increased pressure in the systemic arterial system. "Disruption of the D5R (Drd5) gene in mice causes hypertension that is aggravated by increased salt intake." (PMID 36672619, 2023). "Despite the association with schizophrenia, attention-deficit/hyperactive disorder and substance abuse, gene targeting studies revealed that DRD5 knock-out mice develop hypertension, showing increased blood pressure from 3 months of age." (PMID 31616587, 2019). "The hypertension in Drd5−/− mice is salt-sensitive, as is the case in Drd2−/− mice." (PMID 33535566, 2021). "Our findings indicate that Cetacea are natural knockouts for DRD5 and might offer valuable insights into the mechanisms of some forms of vasoconstriction responses and hypertension in humans." (PMID 31616587, 2019). "Based on the downregulation of AVPR1B and ACE and the upregulation of DRD5, DG treatment may be involved in the rennin-angiotensin system and the receptor-mediated improvement of hypertension." (PMID 24174980, 2013). "A cross-transplantation study using the kidneys from the knockout mice of DRD5, a CKD candidate, shows hypertension and cardiac dysfunctions in this mouse model." (PMID 37123453, 2023). "Besides highlighting a molecular signature for vasoconstriction and blood pressure regulation in Cetacea, naturally occurring DRD5 KO could also provide useful frameworks to gain insight into hypertension and heart failure-induced peripheral vasoconstriction responses in humans." (PMID 31616587, 2019).
colitis (5 papers, 2021 to 2024). Inflammation of the colon. "The deficiency of DRD5 signaling increased colonic M1 macrophages but reduced M2 cells during colitis." (PMID 34001860, 2021). "We found that mice that received DRD5 deficient bone marrow cells had higher M1 polarization and lower M2 polarization than WT donors after colitis." (PMID 34001860, 2021). "We found that WT mice reconstituted with DRD5−/− bone marrow was easier to induce colitis with greater body weight loss, higher DAI score, and shorter colons than WT donors after DSS administration." (PMID 34001860, 2021). "In this study, we further showed the role of DA via DRD5 in regulating the balance of colonic M1/M2 macrophage polarization and explained the underlying mechanism of DA in ameliorating colitis." (PMID 34001860, 2021). "The WT mice that were reconstituted with Drd5−/− bone marrow were more prone to DSS-induced colitis with greater body weight loss, a higher DAI score, shorter colons, and more infiltrating inflammatory cells as well as higher levels of TNFα, IL-6, and CCL2 in serum." (PMID 34884737, 2021). "To further determine whether DRD5 deficiency in immune cells or gut-resident cells contributes to the increased severity of colitis, we firstly generated bone marrow chimeric mice by adoptively transferring WT or DRD5−/− bone marrow cells into lethally irradiated WT recipient mice." (PMID 34001860, 2021). "Accordingly, after imprinting gut tropism in CD4+ T-cells, they were treated with the experimental peptides (TM6C, TM7C, or vehicle) and then i.v. transferred into Drd5−/− recipient mice undergoing DSS-induced colitis." (PMID 39337509, 2024). "An increase in the number of F4/80+ macrophages was observed in the colons of DRD5−/− colitis mice relative to those of WT mice by immunofluorescence staining." (PMID 34001860, 2021). "In this study, we found that DRD5 is highly expressed in colonic macrophages and DRD5 deficiency exacerbates DSS-induced colitis." (PMID 34001860, 2021). "Next, we treated age-matched DRD5 knockout (DRD5−/−) or wild-type (WT) mice with DSS to compare their colitis phenotype." (PMID 34001860, 2021). "The microbiota transfer due to co-housing was not protective against the severe manifestation of subsequently DSS-induced colitis in Drd5−/− mice." (PMID 34884737, 2021). "Given that DRD5 signaling could protect against colitis, we were keen to assess if pharmacological activation of DRD5 could prevent colitis in mice." (PMID 34001860, 2021). "Moreover, the expression of Arg1 in colonic macrophages was markedly reduced in DRD5−/− mice during colitis." (PMID 34001860, 2021). "Collectively, these data suggest DRD5 signaling is indispensable for regulating the balance of colonic macrophage polarization and thereby its protective role in DSS-induced colitis." (PMID 34001860, 2021). "Mice that received Drd5−/− CD45.2/WT CD45.1 bone marrow cells had a higher M1 polarization and a lower M2 polarization than the WT donors after DSS-induced colitis." (PMID 34884737, 2021). "To evaluate the role of DRD5 signaling in colitis, we used the dextran sodium sulfate (DSS) model of colitis in mice." (PMID 34001860, 2021).
gastric cancer (3 papers, 2015 to 2024). A primary or metastatic malignant neoplasm involving the stomach. "Furthermore, regarding the last 10 years of publications about this topic, in gastric cancer, dopamine receptor D5 (DRD5) activation is able to suppress growth tumor if there are specific substances that target this receptor, inducing an autophagic cell death process." (PMID 39767693, 2024). "However, most of the lncRNAs such as DRD5, FMO6P, SNAR-A3 and TPRXL showed in our microarray haven’t been identified and need further investigation to clarify their roles in gastric cancer." (PMID 25928635, 2015).
glioblastoma (3 papers, 2019 to 2021). The most malignant astrocytic tumor (WHO grade IV). "A low expression of DRD5 was presented as being associated with relatively superior clinical outcomes in glioblastoma patients with ONC201." (PMID 31865908, 2019). "Prabhu et. al. recently found a DRD2 + DRD5- biomarker signature that significantly predicts the sensitivity to ONC201 in pre-clinical models and is associated with improved outcomes in patients treated with ONC201 in a Phase II clinical trial for recurrent glioblastoma." (PMID 33557912, 2021).
adenoma (2 papers, 2018). A neoplasm arising from the epithelium. "Nevertheless, the analysis of DRD4 and DRD5 expression may serve as a potential prognostic tool for GH‐producing adenomas." (PMID 29266696, 2018). "However, the molecular study revealed, for the first time, that although the expression of sst3, DRD4 and DRD5 is low in these samples, it is increased in adenomas with suprasellar extension compared with the tumours with no suprasellar growth." (PMID 29670116, 2018).
Alzheimer disease (2 papers, 2013 to 2018). A progressive, neurodegenerative disease characterized by loss of function and death of nerve cells in several areas of the brain leading to loss of cognitive function such as memory and language. "Activation of DRD5 also protected dopaminergic neurons in a PD rat model, promoted neurogenesis in an Alzheimer’s disease mouse model and regulated BDNF expression in the rodent brain." (PMID 30459594, 2018). "Only DRD5 in the neuroactive ligand-receptor interaction pathway was widely studied in cognitive impairment and Alzheimer’s disease." (PMID 23936146, 2013).
attention deficit-hyperactivity disorder (2 papers, 2018 to 2020). A disorder characterized by a marked pattern of inattention and/or hyperactivity-impulsivity that is inconsistent with developmental level and clearly interferes with functioning in at least two settings (e.g. at home and at school). "We also know that increasing binding of D1 receptors has been associated with younger age in suicide, and DRD5 variants have been associated with age of onset in pediatric attention-deficit/hyperactivity disorder (ADHD) patients." (PMID 32824878, 2020). "Additionally, variants in DRD5 and SLC6A3 have been associated with attention deficit hyperactivity disorder (ADHD)." (PMID 32824878, 2020). "The remaining genes, such as GLYCTK, DRD5, NPHP3, and FANCI, were well-characterized pathogenic genes for some other rare diseases with recessive mode of inheritance or multi-gene diseases, such as D-glyceric aciduria, attention deficit-hyperactivity disorder, Meckel syndrome, and Fanconi Anemia." (PMID 30693022, 2018).
cognitive deficits (2 papers, 2013 to 2024). "While little is known about the role of DRD5 in SCZD, DRD5 disruption in some animal models, but not others, is associated with cognitive deficits 79–81 and altered cortical oscillations." (PMID 38463979, 2024).
depression (2 papers, 2020 to 2021). "The second module control downstream FOS to treat depression by targeting the DRD1/DRD5--GNAQ--PLCB1--DAG--PRKCA cascade reaction." (PMID 34867413, 2021).
experimental autoimmune encephalomyelitis (2 papers, 2018 to 2021). An autoimmune demyelinating disease of the central nervous system that is produced experimentally in animals by the injection of homogenized brain or spinal cord in Freund's adjuvant. "Dopamine receptor D5 (DRD5) signaling strengthens suppressive capacity of Tregs, thereby mitigating the manifestation of experimental autoimmune encephalomyelitis (EAE)." (PMID 34458378, 2021). "Previous results have shown that stimulation of dopamine receptor D5 (DRD5) in DCs potentiates their inflammatory behaviour, favouring the development of experimental autoimmune encephalomyelitis (EAE)." (PMID 29619030, 2018).
heart failure (2 papers, 2019 to 2021). Inability of the heart to pump blood at an adequate rate to meet tissue metabolic requirements. "By contrast, SS‐HPT/Drd5 siRNA promotes the progression of left ventricular hypertrophy and accelerates the deterioration of myocardial function into heart failure." (PMID 33717857, 2021). "This study shows that SS‐HPT/Drd5 plasmid complexes may be a therapeutic strategy for the clinical treatment of patients with heart failure." (PMID 33717857, 2021). "The data show a cardiac‐specific beneficial effect of SS‐HPT/Drd5 plasmid on myocardial remodeling and dysfunction, which may provide an effective therapy of patients with left ventricular hypertrophy and heart failure." (PMID 33717857, 2021).
Parkinson disease (2 papers, 2021 to 2025). A progressive degenerative disorder of the central nervous system characterized by loss of dopamine producing neurons in the substantia nigra and the presence of Lewy bodies in the substantia nigra and locus coeruleus. "Of note, in the healthy human substantia nigra, DRD1, DRD3, DRD4, and DRD5 did not exhibit an expression pattern opposite to that of the Parkinson's disease‐associated molecule SNCA." (PMID 41249856, 2025).
somatotropinomas (2 papers, 2018 to 2019). "In conclusion, the systematic evaluation of DRD and SSTR expression in somatotropinomas has revealed an association between the response to SSAs treatment and DRD4, DRD5, SSTR1 and SSTR2 expression." (PMID 29266696, 2018).
asthma (1 paper, 2017). "According to these reports, DRD5 may also engage in some part of the immunological regulation process of T helper 17 cell (Th17) differentiation, which is extensively involved in asthma development." (PMID 28359274, 2017).
Autoimmunity (1 paper, 2018). The occurrence of an immune reaction against the organism's own cells or tissues. "Of note, our findings described here together with previous evidence indicate that DRD5-driven effects in different types of immune cells promote inflammation, supporting the idea that DRD5 results a key molecular target to limit autoimmunity." (PMID 29619030, 2018).
bruxism (1 paper, 2020). Excessive clenching of the jaw and grinding of the teeth. "Motivated by the evidence of a genetic component to bruxism, association studies with common genetic variants have been conducted, suggesting an association exists between genes and bruxism (dopamine receptor D genes DRD2, DRD3, DRD5, and the 5-hydroxytryptamine receptor 2A gene, HTR2A)." (PMID 32471213, 2020).
cardiac hypertrophy (1 paper, 2021). "The heart‐specific increase in D5R expression by SS‐HPT/Drd5 plasmid in the early stage of left ventricular hypertrophy attenuates cardiac hypertrophy and fibrosis by preventing oxidative and endoplasmic reticulum (ER) stress and ameliorating autophagic dysregulation." (PMID 33717857, 2021).
endometrial cancer (1 paper, 2021). Primary or metastatic malignant neoplasm involving the endometrium (mucous membrane that lines the endometrial cavity). "In the case of DRD5, its low expression in endometrial cancer may be related to miR-15a-5p activity." (PMID 34768458, 2021). "Our results, therefore, may suggest that the interaction of this miRNA with DRD5 may play a role in the progression of endometrial cancer by regulating its proliferation." (PMID 34768458, 2021). "In contrast, DRD5 expression was decreased, while DRD2 and DRD3 levels were significantly increased in endometrial cancer." (PMID 34768458, 2021). "It has been observed that as endometrial cancer progresses, expression of CXCL12, GNAL, OPRK1, DRD2, and DRD3 increases while DRD5 and COMT levels are gradually reduced." (PMID 34768458, 2021). "Expression of CXCL12, OPRK1, DRD5, COMT, DRD2, and DRD3 proteins was assessed in the serum of endometrial cancer patients and control group using ELISA." (PMID 34768458, 2021). "Microarray analysis showed that DRD2 was overexpressed regardless of endometrial cancer grade, while COMT and DRD5 showed a significant decrease in expression." (PMID 34768458, 2021).
epilepsy (1 paper, 2019). A brain disorder characterized by episodes of abnormally increased neuronal discharge resulting in transient episodes of sensory or motor neurological dysfunction, or psychic dysfunction. "The following genes are of particular interest to us because of their marked level of transcriptional alteration and their involvement in epilepsy:Dopamine receptor D5 (Drd5)- A D1-type dopamine receptor whose knockdown has been shown to be protective against seizures." (PMID 31455240, 2019).
food allergy (1 paper, 2024). Gastrointestinal disturbances, skin eruptions, or shock due to allergic reactions to allergens in food. "In the same line, the CCR9:DRD5 heteromer seems to be exclusively involved in the infiltration of CD4+ T-cells in the colonic mucosa upon inflammation, and not in homeostatic conditions, as Drd5−/− mice do not develop issues associated with food allergy." (PMID 39337509, 2024).